SOX1 (SRY-box transcription factor 1)
Diseases named in the same sentence as SOX1 in open-access papers (continued):
Sharing a sentence is not in itself a finding about the gene and the disease.
GM1 gangliosidosis (1 paper, 2020). A rare lysosomal storage disorder characterized biochemically by deficient beta-galactosidase activity and clinically by a wide range of variable neurovisceral, ophthalmological and dysmorphic features. "To assess the cellular phenotypes present in GM1 gangliosidosis, we first differentiated the disease-derived iPSC lines into NSCs expressing specific markers, SOX1, PAX6, and NESTIN." (PMID 32302553, 2020).
Hashimoto thyroiditis (1 paper, 2024). An autoimmune disorder caused by the production of autoantibodies against thyroid tissue. "Long-term follow up was documented for two patients with NP-LEMS: one patient with associated Hashimoto’s thyroiditis was followed for 5 years, while the other patient with associated SOX1 antibodies was followed for 11 years following LEMS symptom onset." (PMID 39734633, 2024).
head and neck squamous cell carcinoma (1 paper, 2023). A squamous cell carcinoma that arises from any of the following anatomic sites: lip and oral cavity, nasal cavity, paranasal sinuses, pharynx, larynx, and salivary glands. "However, high expression of SOX1 in late-stage head and neck squamous cell carcinoma leads to poor prognosis." (PMID 37369660, 2023).
lung diseases (1 paper, 2013). "The methyaltion frequencies of 7 genes: MYF6, SIX6, SOX1, RARB, BCL2, PHOX2A and FOLX2 were significantly higher in stage I NSCLC than in non-cancerous lung diseases." (PMID 23599765, 2013). "The methylation frequencies (29.70–64.36%) of 7 genes (MYF6, SIX6, SOX1, RARB, BCL2, PHOX2A and FOLX2) in stage I NSCLC were significantly higher compared with those in non-cancerous lung disease controls (P<0.05)." (PMID 23599765, 2013). "In this study, among the 7 genes which demonstrated hypermethylation in stage I NSCLC compared with non-cancerous lung diseases, 5 genes (MYF6, SIX6, PHOX2A, FOLX2 and SOX1) were found for the first time to be abonormally methylated in NSCLC." (PMID 23599765, 2013). "This study showed that 7 genes (MYF6, SIX6, SOX1, RARB, BCL2, PHOX2A and FOLX2) were frequently methylated in 101 cases of patients with stage I NSCLC, while rarely methylated in 30 patients with non-cancerous lung diseases." (PMID 23599765, 2013).
melanoma (1 paper, 2021). A malignant, usually aggressive tumor composed of atypical, neoplastic melanocytes. "Also, FTO has an oncogenic role and decreases the immunotherapeutic response in melanoma, by m6A demethylation of specific mRNAs such as Programmed cell death protein 1 (PD1), CXC motif Chemokine Receptor 4 (CXCR4) and SRY-Box Transcription Factor 1 (SOX1)." (PMID 33430133, 2021).
MELAS (1 paper, 2020). "First, qPCR analyses of key motor NPC markers revealed that mRNA levels of OLIG2 and SOX1 were consistently higher in MELAS versus c-MELAS." (PMID 32170107, 2020).
microphthalmia (1 paper, 2023). Congenital or developmental anomaly in which the eyeballs are abnormally small. "Moreover, the reduction of SOX1 expression was found in the lens of microphthalmia mutants, whereas PAX2 and PAX6 were down-regulated in the distal part of NR." (PMID 37863656, 2023).
motor neuron disease (1 paper, 2026). "In this study, we report four new cases of paraneoplastic motor neuron disease, two of whom with expression of Sry-like high mobility group box 1 (SOX1) antibody." (PMID 41804301, 2026).
neuroblastoma (1 paper, 2017). Neuroblastoma (NB) is the most common solid, extracranial childhood tumor. "The exception to this pattern was the osteoblast HOS cell line, which expressed the SOX1 gene but not SOX1-OT, and the neuroblastoma SH-SY5Y cell line which presented the opposite pattern." (PMID 28674729, 2017).
Opsoclonus (1 paper, 2019). "There were four cases (16.0%) of abnormal movements: one opsoclonus-myoclonus (anti-GAD65) and three generalized chorea (anti-Ri and anti-Sox1)." (PMID 31694559, 2019).
oral squamous cell carcinoma (1 paper, 2020). "In addition, SOX1 methylation is a useful biomarker for oral squamous cell carcinoma and CC screening." (PMID 32849763, 2020).
prostate tumor (1 paper, 2010). "Further promoter tiling array analysis using two short term cultures primary prostate tumor cell lines, PCSC1 and PCSC2, determined that Sox1, and not Bmx, was methylated in the invasive population of cells." (PMID 20929579, 2010).
serotonin syndrome (1 paper, 2023). Serotoninergic syndrome is characterized by an excess of serotonin in the central nervous system, associated with the use of various agents, including selective serotonin reuptake inhibitors (SSRIs). "In this case study, we report a patient with SOX1 antibodies and altered mental status out of proportion to serotonin syndrome whose symptoms improved with simultaneous treatment of both conditions." (PMID 37946854, 2023). "However, the role of SOX1 antibody in serotonin syndrome has not yet been defined, as a literature search yielded no results." (PMID 37946854, 2023).
small cell carcinoma (1 paper, 2023). A neuroendocrine carcinoma composed of small malignant cells which are often said to resemble "oat cells" under the microscope. "Consistent with the immune response against multiple neural antigens encountered in small cell carcinoma, she was also positive for Hu, SOX-1, and ZIC4 by line blot." (PMID 37841252, 2023).
squamous intraepithelial lesion (1 paper, 2020). "Herein, we assessed the associations of SOX1 promoter hypermethylation with squamous intraepithelial lesion and CC." (PMID 32849763, 2020). "The associations of SOX1 hypermethylation with high-grade squamous intraepithelial lesion (HSIL) and CC risks were evaluated by odds ratios (ORs) and 95% confidence intervals (CIs)." (PMID 32849763, 2020). "In conclusion, the pooled results in this meta-analysis illustrated that DNA methylation of SOX1 could be a promising biomarker for screening CC, high-grade squamous intraepithelial lesion, and CIN3+." (PMID 32849763, 2020).
teratocarcinoma (1 paper, 2017). A germ cell tumor characterized by the presence of an embryonal carcinoma component and a teratoma component. "SOX1 and SOX1-OT were co-detected in teratocarcinoma (NTera) and some breast cancer (MCF7, T47D) cell lines, but not in colon (HCT116, CaCo-2), some breast (MDA-MB-231/361, Hs578T) and cervical (HeLa) cancer cells." (PMID 28674729, 2017).
cancer (52 papers, 2010 to 2025). A tumor composed of atypical neoplastic, often pleomorphic cells that invade other tissues. "The upregulation of SOX1 in the damaged single isolated and suspended cells promotes the cell type transition and transforms the cell into a cancer stem cell, the main cause of tumor formation, and cell proliferation." (PMID 34513834, 2021). "Hypermethylated SOX1 (SOX1m) has been associated with several cancer types, including hepatocellular cancer, lung cancer, urothelial bladder cancer, endometrial cancer, and SCC." (PMID 33376722, 2020). "Nonetheless, hypermethylation in the promoter region and/or somatic mutations in the so-called tumor suppressor genes might cause silencing or inhibition of SOX1, which in turn may result in cancer cell proliferation and migration and finally progression of cervical carcinogenesis." (PMID 33376722, 2020). "This patient, presenting with limbic encephalitis (High-risk phenotype: 3 points), strongly positive anti-SOX1 antibodies (High-risk antibody: 3 points), and a confirmed, consistent underlying SCLC (Cancer found: 4 points), achieved a total score of 10 points." (PMID 41394839, 2025). "The last strategy involves targeting SOX1-positive cancer cells directly by developing antibody-drug or small molecule-drug conjugates to eliminate QCCs." (PMID 37369660, 2023). "According to the latest criteria for PNS, PNS-Care score for this patient is 7 (Anti-SOX1 abs and cancer) which classifies as a probable PNS." (PMID 37083806, 2023). "Quantitative RT–PCR analysis was used to verify that SOX1 controlled the expression of genes related to pathways in cancer, such as LAMB3, FN1, and HES1, and the focal adhesion pathway, including LAMB3 and FN1." (PMID 37190139, 2023). "Basing on the dynamic role of SOX1 in different stages of cancer development, SOX1 would be regarded as a “tumor hypnotist”." (PMID 37369660, 2023). "Unexpectedly, patients with high levels of SOX1 expression in several cancer tissues had a poorer prognosis, as compared to those with low levels of SOX1." (PMID 37369660, 2023). "SOX1, a transcription factor that primarily functions in neurogenesis, has been shown to act as a tumor suppressor in several cancer types, including NPC." (PMID 37369660, 2023). "To gain a better understanding of the role of SOX1 in cancer cells, we had reviewed the existing studies on SOX1 in human cancer." (PMID 37369660, 2023). "In the stage of initiation, cancer cells with low levels of SOX1 have a growth advantage within the population, while those with high levels of SOX1 facilitate cancer cell survival against treatment of chemo drugs." (PMID 37369660, 2023). "HHEX caused a repression of a series of neural stemness genes or/and genes promoting cancer, Sox1, Sox2, Myc, Cdh2, Vim, Hes1, Zic1, Pax6, Ezh2, and Lsd1." (PMID 34595169, 2021). "Simultaneous methylation of SOX1 + HOXA9 exhibited a sensitivity of 66.67% with a specificity of 96.0% (AUC = 0.85) for cancer detection in serum cell-free DNA." (PMID 34778370, 2021). "Simultaneous methylation of HIC1 + SFRP1 and DAPK1 + SOX1 exhibited sensitivity of 78.82 and 72.94%, respectively with specificity of 77.14% (AUC = 0.87 for both gene panels) for cancer detection." (PMID 34778370, 2021). "The best therapeutic strategy is targeting of stem cell marker genes (SOX2, SOX1, and vimentin, etc.)to reduce the population of cancer stem cells." (PMID 34513834, 2021). "The performance of all the two-gene marker panels (HOXA9 + SOX1) and (HIC1 + SOX1) was found significant and the gene panels differentiated cancer vs normal with a higher accuracy in serum samples." (PMID 34778370, 2021).
cancer (continued). "SOX1 is also known to bind to β-catenin to attenuate Wnt signalling, while dysregulated Wnt signalling has been reported in many cancer types." (PMID 33202879, 2020). "Results presented here will inform future experimental investigations on the differential regulation of SOX1 transcriptional function in neural stem cell fate and in cancer." (PMID 33202879, 2020). "Future mutational analyses experiments will be needed to better evaluate the role of these residues and their link to SOX1 regulation, both as a neural marker and for its role in cancer development." (PMID 33202879, 2020). "SOX1 function in neural stem cell maintenance has been studied widely, but little is known about the role of SOX1 in cancer." (PMID 33202879, 2020). "It has been previously shown that SOX1 is a negative regulator of WNT/β-catenin signaling in several types of cancer justifying its tumor suppressor activity." (PMID 28425506, 2017). "Regarding the methylation status of SOX1 gene, data are limited to various types of cancers, while for neural differentiation experimental data are lacking." (PMID 28886103, 2017). "High methylation of SOX1 can also serve as a biomarker for hidden cancer in endometrial atypical hyperplasia (manuscript accepted for publication)." (PMID 26057869, 2015). "Whereas non-SP cells formed fewer and slower-growing tumours, SP cells over-expressed many genes associated with cancer stem cell and drug resistance: ABCG2, FGF1, IGF1, MYC, SOX1/2, WNT1, as well as genes involved in angiogenesis, Notch and Hedgehog pathways." (PMID 20424609, 2010). "Additionally, experimental research is needed to elucidate the detailed mechanisms by which HOXA9 and SOX1 methylation influence cancer progression, and to explore its potential as a therapeutic target." (PMID 40699796, 2025). "SOX1 suppresses Rac1 activity, a key member of the Rho family of GTPases that regulates actin cytoskeletal remodeling and membrane protrusion formation—critical steps in cancer cell motility." (PMID 40699796, 2025). "Patients exhibiting high methylation in SOX1, PAX1, and ZNF582 exhibited increased risk of cancer." (PMID 40256126, 2025). "Furthermore, inducible SOX1 expression significantly suppressed colony formation and cancer invasion compared with the control group." (PMID 37190139, 2023). "SOX1, a well-known tumor suppressor, delays malignant progression in most cancer types." (PMID 37369660, 2023). "Based on the evidence presented above, we proposed a hypothesis to explain the conflicting role of tumor suppressor SOX1 in promoting survival of cancer cells after therapy." (PMID 37369660, 2023). "This could also help us understand the molecular mechanisms of SOX1 in different stages of cancer progression." (PMID 37369660, 2023). "The high expression of SOX1 within individual cancer cells could potentially indicate chemotherapy resistance in NPC, and it might be of significance to propose feasible targeting strategies for tumor recurrence after clinical interventions." (PMID 37369660, 2023). "Moreover, overexpression of SOX1 significantly represses cancer growth and invasion in vitro and in vivo." (PMID 37190139, 2023). "Upregulation of SOX1 was recently shown to suppress growth of human cancers." (PMID 34876142, 2021). "The same applies to patients with high-risk phenotypes along with intermediate risk antibodies who show particular demographic characteristics (older age and smoking) or have concurrent antibodies with strong cancer association (e.g., P/Q VGCC and SOX1 antibodies in LEMS)." (PMID 34006622, 2021). "Therefore, miR-155 acts an oncogene to directly regulate SOX1 expression and promote cancer progression in GC." (PMID 32675943, 2020). "Further research will determine whether blocking K83 acetylation can modify SOX1 function in neurodevelopment and cancer." (PMID 33202879, 2020).
cancer (continued). "Further investigation is needed to explore how SOX1 regulates cancer cell differentiation and whether the interaction between SOX1 and β-catenin is involved in this regulation." (PMID 25427424, 2014). "The epigenetic silencing of SOX1 through promoter hypermethylation, as observed in our cohort, may thus lead to the aberrant activation of the Wnt pathway, contributing to the increased proliferation and survival of cancer cells." (PMID 40699796, 2025). "Therefore, a positive result for SOX1-abs based only in the commercial line blot does not necessarily indicate that the patient has an underlying cancer or should initiate immunotherapy." (PMID 37207233, 2023). "Therefore, SOX1 may function as a “tumor hypnotist”, facilitating cancer cell survival upon exposure to chemotherapy and other unfavorable conditions." (PMID 37369660, 2023). "In addition, SOX1 was also reported to be involved in the regulation of cancer stemness." (PMID 33531993, 2021). "Additionally, the link between SOX1 and β‐catenin has been shown in various carcinomas." (PMID 32918341, 2020). "Inspired by previous reports suggesting a paraneoplastic etiology in rare cases of cancer-associated NMOSD, this is the first study systematically investigating the seroprevalence of onconeural antibodies (anti-Hu, Yo, Ri, CV2/CRMP5, Ma1, Ma2, Zic4, SOX1, Tr, and amphiphysin) in NMOSD patients." (PMID 28068933, 2017). "Here, via multiomics analyses of 314 SCLCs, we found that the ASCL1+/MKI67+ and ASCL1+/CRIP2+ clusters accounted for 74.38% of the 190,313 SCLC cancer cells from 39 patients, with the ASCL1+SOX1+ stem-like cell cluster across SCLC subtypes." (PMID 40925909, 2025). "Nearly all SOX genes, including SOX1, SOX2, SOX7, and SOX10, have been shown to influence glioma progression and exhibit oncogenic functions across multiple cancer types." (PMID 40159622, 2025). "The SOX1 gene is embedded within an intron of a SOX1OT, and their expressions correlate during neural differentiation as well as in cancer cell lines, such as teratocarcinoma (NTera) and breast carcinoma cell lines." (PMID 37047365, 2023). "Having in mind that SOX1 has oncogenic activity in GBM and that SOX1 and SOX1OT expressions correlate in some cancer cell lines, it would be interesting to analyze SOX1OT expression in GBM." (PMID 37047365, 2023). "However, due to the limitations of the artificial gene expression model, it remains unknown how SOX1 is induced in individual cancer cells to enter quiescence or how QCCs decrease SOX1 expression to resume proliferation in response to environmental alterations." (PMID 37369660, 2023). "To find out how tumor suppressor SOX1 promoted cancer cell survival after therapy, we conducted RNA-seq analysis on NPC cells with high versus low expression of SOX1." (PMID 37369660, 2023). "When switching to a paclitaxel-free culture environment, the cells with decreased levels of SOX1 re-express MYC, resulting in increased abundance of proliferative cancer cells." (PMID 37369660, 2023). "For cancer samples, DAPK1, MLH1 and MALAT1 had higher expression, and MEG3, TIMP3 and SOX1 had lower expression when compared to normal samples." (PMID 35682732, 2022). "For cancer samples, the expression level was higher than in normal samples for DAPK1, MLH1 and MALAT1, and lower for MEG3, TIMP3 and SOX1." (PMID 35682732, 2022). "We compared the expression levels (mRNA) of SOX B1 family members (SOX1, SOX2 and SOX3) in various cancers and normal tissue using the ONCOMINE database." (PMID 34953010, 2022). "The other two-gene cassette comprising of SOX1+HIC1 exhibited combined sensitivity of 80.0% with a specificity of 96% in serum CFDNA [AUC = 0.93] in differentiating malignant EOC samples and cancer-free healthy control serum samples." (PMID 34778370, 2021).